U3 (Small nucleolar RNA U3 )
Synonyms: LOC124901221
Gene: Small nucleolar RNA gene on chromosome 5 (149,695,748 to 149,695,959, reverse strand). Ensembl gene ENSG00000221043.
Gene Ontology:
Biological process: RNA processing
Cellular component: nucleolus
Homologues: Orthologues: chimpanzee U3 (98% identical), macaque U3 (92% identical). Paralogues in human: U3 (76% identical), SNORD3P1 (75% identical), SNORD3D (75% identical), U3 (75% identical), SNORD3E (74% identical), SNORD3G (74% identical), U3 (74% identical), U3 (73% identical), SNORD3H (72% identical), U3 (72% identical), U3 (71% identical), U3 (70% identical), and 14 more.